REN (renin)
Diseases named in the same sentence as REN in open-access papers (continued):
Sharing a sentence is not in itself a finding about the gene and the disease.
hyperuricemia (continued). "All-causes mortality and ESKD risks were analyzed by multivariable-adjusted Cox proportional hazards models (adjusted for age, sex, smoke, previous coronary arterial disease, blood pressure, and medications for hyperlipidemia, hyperuricemia and renin–angiotensin system inhibitors)." (PMID 35459096, 2022). "In the present study, 63.6% of the patients were taking ACE inhibitors or ARBs at baseline, which could have attenuated the potential effects of hyperuricemia on the activity of the renin-angiotensin system." (PMID 33765101, 2021). "For example, hyperuricemia may affect arterial pressure by activating the renin-angiotensin system and reducing nitric oxide synthase activity." (PMID 28842671, 2017). "In addition, it has been reportedthat hyperuricemia increases juxtaglomerularrenin expression and decreases macula densaneuronal nitric oxide synthase expression.Thus, uric acid may cause renal injury by interactingsynergistically with the renin-angiotensin systembeside oxidative stress." (PMID 26246875, 2015). "In addition, hyperuricemia itself has been shown to activate the renin-angiotensin system, which increases sodium resorption." (PMID 26618358, 2015). "Second, hyperuricemia may induce direct renal injury through the activation of the renin-angiotensin aldosterone system (RAS)." (PMID 24739095, 2014). "Moreover, fundamental changes in renal vascular and vasoconstriction mechanisms that occur in AKI are similar to those in hyperuricemia, including renin-angiotensin-aldosterone system (RAAS) activation, oxidative stress, nitric oxide reduction, and inflammation." (PMID 37073630, 2023). "Moreover, chronic hyperuricemia stimulates the renin-angiotensin system and inhibits endothelial nitric oxide (NO) release, which may lead to renal vasoconstriction and increases blood pressure." (PMID 31408958, 2019). "Hyperuricemia inhibits endothelial nitric oxide synthesis and release, and stimulates the renin-angiotensin-aldosterone system; moreover, urate crystals may damage the arterial intima, leading to oxidative stress, vascular inflammation, and elevated blood pressure." (PMID 27663794, 2016). "Hyperuricemia may be a marker and itself possibly be responsible for microvascular damage through inhibition of endothelial nitric oxide synthetase and activation of the renin-angiotensin system." (PMID 27490538, 2016). "Moreover, rat models, in which oxonic acid is used to induce hyperuricemia, indicate that hyperuricemia provokes a diversity of pathophysiological changes, e.g., activation of the renin-angiotensin system, decreased creatinine clearance, and severe arteriolopathy of the afferent arteriole." (PMID 24433285, 2014). "Hyperuricemia often precedes development of obesity and T2D, and clinical evidence suggests that hyperuricemia may mediate the association between SSB consumption and hypertension through the development of renal disease, endothelial dysfunction, and activation of the renin–angiotensin system." (PMID 31398911, 2019). "Although not completely elucidated, urate-lowering therapy may decrease blood pressure by blocking the renin–angiotensin system (RAS), which is activated in hyperuricemia." (PMID 40248713, 2025). "Moreover, Our study also suggests that some antihypertensive drugs with central action, α and β blockers, renin inhibitors and vasodilators may be associated with increased risk of hyperuricaemia, gout or related AEs, which has not been reported in previous studies." (PMID 36699079, 2022). "Renovascular hypertensive patients with severe hyperuricemia had higher BP and left ventricular hypertrophy, indicated by increased LVMI, which may result from activation of the renin-angiotensin system, reduction of vascular nitric oxide production, or activation of distal nephron sodium channels." (PMID 30838132, 2019).
vitamin D deficiency (102 papers, 2010 to 2026). A nutritional condition produced by a deficiency of VITAMIN D in the diet, insufficient production of vitamin D in the skin, inadequate absorption of vitamin D from the diet, or abnormal conversion of vitamin D to its bioactive metabolites. "Vitamin D deficiency is linked to upregulated renal renin–angiotensin–aldosterone system activity and TGF-β1-driven fibrosis, while impaired glucocorticoid signaling attenuates the suppression of pro-inflammatory cytokines in renal tissues." (PMID 41041131, 2025). "In both the supine and standing positions, vitamin D deficiency hypertensive patients had lower direct renin, aldosterone, and ARR values than those with vitamin D non-deficiency." (PMID 41048520, 2025). "Additional abnormalities included hypomagnesemia in three patients (mean serum magnesium: 0.74 mmol/L), vitamin D deficiency in two (mean 25OHD: 27.6 ng/mL), hyperphosphatemia in two (mean phosphorus 1.41 mmol/L), and universal elevated plasma renin activity." (PMID 40893942, 2025). "Vitamin D deficiency also plays a crucial role in upregulating inflammatory cytokines and activating the renin-angiotensin-aldosterone system (RAAS)." (PMID 39944452, 2025). "One animal study showed that [1,25(OH)2D] favors suppression of the biosynthesis of renin, whereas vitamin D deficiency stimulates its synthesis." (PMID 38084240, 2023). "Both experimental and clinical trials linked vitamin D deficiency to the excessive activation of the RAAS with increased expression of the renin gene, higher plasma renin activity, and elevated plasma aldosterone and angiotensin II levels." (PMID 38002259, 2023). "Vitamin D deficiency activates the renin-angiotensin-aldosterone system (RAAS), which increases blood pressure and affects the cardiovascular system." (PMID 37351236, 2023). "The results of the present study show that vitamin D deficiency is common in Urumqi, Xinjiang, China and vitamin D levels are negatively correlated with renin levels." (PMID 35814306, 2022). "Vitamin D deficiency is thought to contribute to sustained renin‐angiotensin‐aldosterone axis activation." (PMID 32557856, 2020). "Stimulation of the renin-angiotensin-aldosterone system has been proposed as a mechanism linking vitamin D deficiency and cardiovascular disease." (PMID 27649235, 2016). "Increased renin secretion has also been proposed as a mechanism linking vitamin D deficiency and cardiovascular events." (PMID 27649235, 2016). "Vitamin D deficiency causes to “up-regulation of renin-angiotensin-aldosterone system” and results in hypertrophy of cardiovascular smooth muscle cells." (PMID 24734087, 2014). "Vitamin D deficiency has been associated with abnormal cardiac relaxation, proliferation, and increased cardiac renin gene expression." (PMID 25268137, 2014). "Vitamin D deficiency predisposes to up-regulation of the renin–angiotensin–aldosterone system and hypertrophy of the vascular smooth muscle cells." (PMID 25528383, 2014). "Previous studies have shown strong evidences that vitamin D deficiency led to an upregulation of the renin-angiotensin system." (PMID 25048368, 2014). "Mice with diet-induced vitamin D deficiency showed increased systolic and diastolic blood pressure, high plasma renin, and decreased urinary sodium excretion." (PMID 23349943, 2013). "Vitamin D deficiency activates the renin-angiotensin-aldosterone system, can predispose to hypertension and left ventricular hypertrophy." (PMID 23346457, 2012). "The VDR knockout mouse, an animal model emulating vitamin D deficiency, displays increased blood pressure, serum angiotensin, and tissue renin." (PMID 23346457, 2012).
vitamin D deficiency (continued). "Maternal vitamin D deficiency is accompanied by changes in the renal expression of podocin, renin and AT1 receptors, and it delays the maturity of the glomeruli, by extending nephrogenesis." (PMID 22927914, 2012). "A direct effect of FGF23 to suppress ACE2 provides an alternative explanation for the recently proposed associations between vitamin D deficiency, activation of the renin-angiotensin system and regulation of α-Klotho expression." (PMID 22970174, 2012). "In normal mice, vitamin D deficiency stimulates renin expression, whereas injection of 1,25-dihydroxyvitamin D3[1,25(OH)2D3] reduces renin synthesis." (PMID 20049157, 2010). "Moreover, evidence suggests that vitamin D deficiency activates the renin–angiotensin–aldosterone system, leading to increased vascular tone and arterial stiffness, both of which are strong predictors of overall cardiovascular disease risk." (PMID 40492481, 2025). "Another postulated mechanism is that vitamin D deficiency may activate the renin–angiotensin–aldosterone system that might, in turn, cause arterial changes." (PMID 39940336, 2025). "Evidence suggests an inverse relationship between vitamin D levels and the risk of pre-HTN and HTN, explained by mechanisms linking vitamin D deficiency to renin-angiotensin system activation, vascular endothelial dysfunction, disruptions in calcium homeostasis, and free radical production." (PMID 39980554, 2025). "In the human population, vitamin D deficiency may contribute to chronic overactivation of the renin–angiotensin system (RAS), explaining its connection to various cardiovascular and neuroinflammatory disorders." (PMID 41464543, 2025). "Despite direct renin values being higher in the vitamin D deficiency group." (PMID 41048520, 2025). "Moreover, vitamin D deficiency also elevates blood pressure via effects on the renin-angiotensin-aldosterone system and atrial stiffness." (PMID 41141155, 2025). "In addition, the role of vitamin D deficiency in renin-angiotensin-aldosterone system activation, abnormal nitric oxide regulation, oxidative stress, and dysregulation of inflammatory pathways have been proposed." (PMID 38380006, 2024). "This may be related to the activation of the renin-angiotensin system, abnormal nitric oxide regulation, oxidative stress, or alterations in inflammatory pathways following vitamin D deficiency." (PMID 39691689, 2024). "Vitamin D deficiency may be associated with many risk factors include inflammatory pathways, nitric oxide regulation, oxidative stress, and renin-angiotensin-aldosterone system activation." (PMID 37149586, 2023). "Whether this is due to the effect of vitamin D deficiency in the pathogenesis of IgAN or due to its interaction with the renin-angiotensin system needs to be determined." (PMID 36650464, 2023). "Previous investigations have shown the association between vitamin D deficiency and kidney disease progression which may be in part attributed to the renin-angiotensin-aldosterone system (RAAS) by vitamin D." (PMID 38084240, 2023). "For example, vitamin D deficiency might activate the renin-angiotensin-aldosterone system and increase the CVD risk." (PMID 36451743, 2022). "Moreover, other non-inflammatory factors related to kidney dysfunction include metabolic acidosis, renin-angiotensin-aldosterone system, uremic toxins, and vitamin D deficiency." (PMID 35330131, 2022). "Moreover, vitamin D deficiency stimulates renin expression in normal mice, whereas the injection of 1,25(OH)2D reduces renin synthesis." (PMID 33809311, 2021). "Importantly, miR-106b knockout prevented the elevation in blood pressure and plasma renin induced by vitamin D deficiency." (PMID 32968066, 2020). "Vitamin D deficiency in pregnancy may influence blood pressure, and the renin–angiotensin system in the offspring, resulting in increased CVD risk." (PMID 30786861, 2019).
vitamin D deficiency (continued). "Moreover, vitamin D deficiency stimulated renin expression in normal mice, whereas injection of 1,25(OH)2D reduced renin synthesis." (PMID 30057603, 2018). "It is hypothesized that vitamin D deficiency increases blood pressure through the renin-angiotensin system." (PMID 29977597, 2018). "Vitamin D deficiency stimulates renin-angiotensin-aldosterone system, which may increase angiotensin II expression." (PMID 29850540, 2018). "Several study have reported that both elevated FGF23 and vitamin D deficiency may cause left ventricular hypertrophy via activation of the calcineurin pathway and the renin-angiotensin-aldosterone system, respectively." (PMID 28747700, 2017). "Vitamin D may suppress the renin biosynthesis, and human studies have shown increased levels of renin and angiotensin II in subjects with vitamin D deficiency." (PMID 28686645, 2017). "Moreover, vitamin D deficiency stimulates renin expression in normal mice, whereas injection of 1,25(OH)2D reduces renin synthesis." (PMID 28912809, 2017). "Vitamin D deficiency has been shown to down-regulate the renin-angiotensin system." (PMID 27764169, 2016). "In animal models, vitamin D deficiency has been associated with increased renin secretion." (PMID 27649235, 2016). "As the sympathetic nervous system stimulates renin secretion, increased sympathetic nervous system activity could mediate an association between vitamin D deficiency and renin secretion." (PMID 27649235, 2016). "Vitamin D deficiency might activate the renin-angiotensin system, increase serum level of parathyroid hormone (PTH), and decrease insulin-like growth factor 1 (IGF-1) level." (PMID 25822845, 2015). "Interestingly, numerous studies in mice document that vitamin D signaling suppresses the renin-angiotensin-system and that vitamin D deficiency is associated with an increased activity of the renin-angiotensin-system." (PMID 25071589, 2014). "As vitamin D inhibits renin release, vitamin D deficiency is believed to increase RAAS activity." (PMID 25528363, 2014). "Furthermore, vitamin D deficiency might affect the renin-renin–angiotensin–aldosterone system (RAAS), increasing oxidative stress and reactive oxygen species production, thus elucidating its association with kidney stone development." (PMID 41149617, 2025). "Additionally, vitamin D deficiency may contribute to increased blood pressure through influence on the renin-angiotensin-aldosterone system and atrial stiffness." (PMID 41141155, 2025). "However, few research has revealed whether vitamin D deficiency affects the value of direct renin, aldosterone concentration and ARR." (PMID 41048520, 2025). "Vitamin D deficiency may facilitate the initiation and development of AF through proliferative and pro-inflammatory actions of the renin–angiotensin system and excess catecholamine, interstitial fibrosis in the left atrium, and various electrical anomalies that cause fibrillatory conductions." (PMID 36836027, 2023). "Moreover, vitamin D deficiency may cause over-activation of the renin-angiotensin system (RAS), which aggravates extracellular matrix (ECM) deposition and lung fibrosis." (PMID 28607392, 2017). "The associations found in clinical studies and the supporting mechanistic studies make it plausible that vitamin D deficiency could indeed contribute to an inappropriately elevated renin levels, as a mechanism for progression of CKD and/or cardiovascular disease." (PMID 26000281, 2015). "Vitamin D deficiency has been shown to activate the RAAS, resulting in higher renin levels, increased blood pressure, and decreased urinary sodium excretion in animal models." (PMID 41464543, 2025). "Vitamin D deficiency, which is more common in blacks, tends to upregulate the RAAS by increasing renin and aldosterone production." (PMID 34531372, 2021). "A large number of patients in both study groups had vitamin D deficiency and elevated FGF-23 and renin concentrations." (PMID 30057603, 2018).
vitamin D deficiency (continued). "Vitamin D deficiency heightens RAAS activity 30, 43, whereas vitamin D supplementation seems to reduce renin synthesis and plasma renin activity." (PMID 27058906, 2016). "Putative nontraditional risk factors also include activation of the renin–angiotensin system and sympathetic nerve activity, as well as reduced bioavailability of nitric oxide, platelet dysfunction, vitamin D deficiency, and hyperphosphatemia." (PMID 33538236, 2021). "Vitamin D is a negative endocrine RAS modulator and inhibits renin expression and generation and it appears likely that vitamin D deficiency amelioration would limit the COVID-19 BK storm." (PMID 33142828, 2020). "Furthermore, vitamin D is a known regulator of cardiovascular and renal function mediated via the interaction of Vitamin D receptors within the renin-angiotensin-aldosterone system (RAAS), highlighting the multisystemic effects of vitamin D deficiency." (PMID 32878330, 2020). "Finally, we observed that hypertensive patients with vitamin D deficiency had significantly greater aldosterone and aldosterone-to-renin ratio (ARR) values than those having vitamin D non-deficiency." (PMID 41048520, 2025). "Vitamin D insufficiency upregulates the renin-angiotensin system (RAS) and the NF-κB pathway, decreases the nitric oxide synthase transcription in vascular endothelial cells, increases inflammation and oxidative stress, and therefore may be a risk factor for progression of kidney disease." (PMID 36650464, 2023). "Vitamin D deficiency did not increase SBP or DBP or plasma renin in Ddit3−/− mice." (PMID 32968066, 2020). "Vitamin D insufficiency may obscure any expected relationship between it and renin levels." (PMID 23316249, 2012). "Vitamin D deficiency (VDD) is commonly observed in HF patients and may exacerbate disease progression through various pathophysiological mechanisms, including activation of the renin–angiotensin–aldosterone system, inflammation, oxidative stress, and impaired calcium homeostasis." (PMID 40507108, 2025).